RAB10 (RAB10, member RAS oncogene family)
Diseases named in the same sentence as RAB10 in open-access papers (continued):
Sharing a sentence is not in itself a finding about the gene and the disease.
gastric cancer (8 papers, 2021 to 2025). A primary or metastatic malignant neoplasm involving the stomach. "Hsa_circ_0001658 suppresses the autophagy of gastric cancer cells via the miR-182/RAB10 axis and sponges miR-182 to suppress the expression of RAB10." (PMID 38338839, 2024). "Reduced miR-182 expression inhibits RAB10 expression, reducing cell viability and autophagy and promoting apoptosis in gastric cancer cells." (PMID 37181652, 2023). "Moreover, upregulation of RAB10 counteracted the effects of miR-182 on cell viability, autophagy, and apoptosis in gastric cancer cells." (PMID 40936702, 2025). "Therefore, silencing circ_0001658 inhibits RAB10 expression by sponging miR-182, thereby reducing cell viability, inhibiting autophagy, and promoting apoptosis in gastric cancer cells." (PMID 40936702, 2025). "Here we identified a novel form of ALK fusion, a case of GC with RAB10-ALK fusion, and this is the first report of ALK fusion in gastric cancer." (PMID 33692962, 2021).
Alzheimer disease (7 papers, 2017 to 2023). A progressive, neurodegenerative disease characterized by loss of function and death of nerve cells in several areas of the brain leading to loss of cognitive function such as memory and language. "Furthermore, a variant of Rab10 was identified as potentially protective in Alzheimer’s disease." (PMID 38110990, 2023). "We conclude that Rab10+/− mice described here can be a valuable tool to study the mechanisms of resilience in Alzheimer’s disease (AD) model mice and to identify novel therapeutical targets to prevent cognitive decline associated with normal and pathologic aging." (PMID 37156612, 2023). "Gene-based tests conducted in the CCS and Alzheimer’s Disease Neuroimaging Initiative (ADNI) samples using SKAT-O resulted in a significant association for RAB10 (p value = 0.002), but not SAR1A (p value = 1.00)." (PMID 29183403, 2017). "Finally, Rab10 expression levels were reported as significantly increased in Alzheimer’s disease brain, suggesting that Rab10’s role as a ciliogenesis inhibitor may also be relevant to Alzheimer’s disease pathology." (PMID 30398148, 2018).
glioma (6 papers, 2018 to 2024). A benign or malignant brain and spinal cord tumor that arises from glial cells (astrocytes, oligodendrocytes, ependymal cells). "In another earlier study, the modulation of miR-574-5p/RAB10 expression by PSMB8-AS1 promoted the proliferation of glioma cells." (PMID 36737692, 2023). "It has been reported that circ_PTN can affect the function of glioma cells through targeting miR-122/SOX6 or miR-432-5p/RAB10 axis." (PMID 34853725, 2021). "PSMB8-AS1 activated by ELK1 promotes cell proliferation in glioma via regulating miR-574-5p/RAB10." (PMID 35024796, 2022). "Shen once reported that ELK-1 could activate PSMB8-AS1, which could modulate miR-574-5p/RAB10 and promote cell proliferation in glioma." (PMID 34281486, 2021).
breast carcinoma (5 papers, 2020 to 2025). "However, the association between RAB10 and immune infiltrating cells in breast cancer remains unclear." (PMID 37709911, 2023). "FAM49B can also stimulate breast cancer cell proliferation and migration through the Rab10/TLR4 pathway." (PMID 36499755, 2022). "Our study indicates that levels of proteins PERP, GNAS2, GNA13, ITB1, and RAB10 in EVs emitted by cultured breast cancer cells correlate with sensitivity of these cells to trastuzumab." (PMID 33023655, 2020). "RAB10, a member of the small GTPase family, has complex biological functions, but its role in breast cancer (BC) remains unclear." (PMID 37709911, 2023). "This study showed that FAM49B can activate the proliferation and metastasis of BC cells through the ELAVL1/Rab10/TLR4 pathway, and the malignant degree and aggressiveness of breast cancer with high expression of FAM49B were significantly increased." (PMID 34645466, 2021). "Other potential biomarkers of breast cancer trastuzumab response are proteins GNAS2, GNA13, RAB10, and ITB1 that we discovered via proteomics-based analysis." (PMID 33023655, 2020). "Our data indicate that PERP, GNA13, GNAS2, ITB1, and RAB10 are upregulated in EVs derived from trastuzumab-sensitive but not from trastuzumab-resistant breast cancer cells in culture." (PMID 33023655, 2020). "However, the effect of trastuzumab on RAB10 is not unique to one model system as we also observed RAB10 upregulation in EVs derived from the blood of one of the breast cancer patients undergoing trastuzumab-based therapy that did benefit from the treatment." (PMID 33023655, 2020). "Interestingly, unlike the case with EVs, trastuzumab did not upregulate all of the indicated proteins in the breast cancer cells themselves: the drug upregulated RAB10 and PERP in BT-474 cells but downregulated ITB1 and did not change the levels of GNAS2 and GNA13 in the cells." (PMID 33023655, 2020).
esophageal squamous cell carcinoma (5 papers, 2020 to 2025). Esophageal squamous cell carcinoma (ESCC) is a type of esophageal carcinoma (EC) that can affect any part of the esophagus, but is usually located in the upper or middle third. "Coincidently, a recent study showed that Rab10, which was listed amongst our 13 predicted targets, was a miR-378a-3p target in the development of esophageal squamous cell carcinoma." (PMID 32257967, 2020). "Importantly, a more recent paper about esophageal squamous cell carcinoma reported that miR-378a-3p targeted Rab10 during the process of this cancer development." (PMID 32257967, 2020).
liver cancer (4 papers, 2015 to 2022). An epithelial or non-epithelial malignant neoplasm that arises from the liver. "Although recent study has shown that RAB10 was high expressed in some liver cancer tissue samples, the biological and clinical significances of RAB10 in HCC remain largely unclear." (PMID 28460436, 2017). "Recent study has shown that RAB10 was high expressed in some liver cancer tissue samples." (PMID 28460436, 2017).
neuroblastoma (4 papers, 2017 to 2025). Neuroblastoma (NB) is the most common solid, extracranial childhood tumor. "Furthermore, overexpression of Rab10 in mouse neuroblastoma cells significantly increases Aβ production with full length APP levels being unaffected, suggesting that Rab10 function occurs in the later stages of the amyloidogenic pathway." (PMID 35625878, 2022). "To examine previous reports of biochemical interactions between RAB10 and APP and between SAR1A and APP, we examined the effects of overexpressing and silencing RAB10 and SAR1A on APP processing in mouse neuroblastoma cells." (PMID 29183403, 2017).
Anxiety (2 papers, 2023 to 2025). Intense feelings of nervousness, tension, or panic often arise in response to interpersonal stresses. "In addition, we have shown that leucine can largely rescue deficiency in protein synthesis and neuropeptide release in Rab10-depleted neurons, providing a potential treatment for disorders associated with neuropeptide abnormalities such as depression and anxiety." (PMID 40172954, 2025).
Crohn disease (2 papers, 2021 to 2022). A gastrointestinal disorder characterized by chronic inflammation involving all layers of the intestinal wall, noncaseating granulomas affecting the intestinal wall and regional lymph nodes, and transmural fibrosis. "Variants in LRRK2 within the ROC, COR, kinase, and WD40 domains have been linked to increased risk for PD or Crohn’s disease and have been reported to lead to increased Rab10 phosphorylation." (PMID 34145320, 2021). "Finally, we showed that missense variants in LRRK2 associated with reduced risk for PD and Crohn’s disease lead to lower levels of Rab10 phosphorylation, suggesting that these variants may lower disease risk by reducing the activity of the LRRK2 signaling pathway." (PMID 34145320, 2021).
Sepsis (2 papers, 2024 to 2025). Sepsis is defined as life-threatening organ dysfunction caused by a dysregulated host response to infection. "To test whether acute and systemic inflammation in mice might affect extracellular pT73-Rab10 to total Rab10 ratios, we introduced a polymicrobial sepsis challenge to outbred CD-1 mice that caused large increases in serum concentrations of IFNγ and TNF." (PMID 38862989, 2024). "Circ-TDRD9 enhances the expression of Rab10 through the miR-223-3p/Rab10 axis, promoting acute lung injury induced by sepsis." (PMID 39996735, 2025). "For example, a diminished level of total Rab10 in serum, such as through immune cell depletion or that we observed in sepsis, may not necessarily reflect diminished LRRK2 activity should the ratio of pT73-Rab10 to total Rab10 persist at normal levels." (PMID 38862989, 2024).
synucleinopathy (2 papers, 2022 to 2024). A neurodegenerative disease that is characterized by the abnormal accumulation of aggregates of alpha-synuclein protein in neurons, nerve fibers or glial cells. "In conclusion, this is a rare autopsy report of a patient with PD harboring LRRK2 G2385R variant, showing elevated phosphorylation of Rab10, a substrate of LRRK2, and characteristic pathology as synucleinopathy." (PMID 35931783, 2022).
tauopathies (2 papers, 2022 to 2025). "Two interactome studies have also identified Rab10 as an interactor with tau inclusions across tauopathies." (PMID 40661559, 2025). "Intriguingly, phospho-Rab10 was colocalized in AT8-positive tau, but not in amyloid plaques, in tauopathy, including AD48." (PMID 35931783, 2022).
asthenozoospermia (1 paper, 2023). "The proteins RAB10, RAB3D, RAB27A, and MLPH that showed a lower abundance level in asthenozoospermia and a higher abundance level in oligoasthenozoospermia were either Ras-related or were associated with sperm motility and capacitation." (PMID 37048090, 2023).
Cachexia (1 paper, 2023). Severe weight loss, wasting of muscle, loss of appetite, and general debility related to a chronic disease. "We found that the modulation of ECM secretion via SPARC or Rab10 can ameliorate the cachexia phenotype." (PMID 38014610, 2023).
cocaine addiction (1 paper, 2024). "However, the expression patterns of Rab10 during cocaine treatment and its potential effects (and mechanisms underlying these effects) on cocaine addiction remain largely unexplored." (PMID 39669198, 2024). "However, the link between Rab10 deficits and the associated receptor’s membrane expression and function in the context of cocaine addiction remains unclear." (PMID 39669198, 2024). "Further examination of the RNAseq data to identify genes that are more likely to affect cocaine addiction revealed 367 differentially expressed genes between Rab10 high- and low-expression groups (unpaired t-tests; FDR p < 0.05 and |fold change| > 1.5)." (PMID 39669198, 2024).
Cognitive impairment (1 paper, 2024). Abnormal cognition is characterized by deficits in thinking, reasoning, or remembering. "Indeed, increased phosphorylation of Rab10 was observed in the urine EVs of patients with PD with LRRK2 mutations compared to controls, and it further correlated with the patients’ motor and cognitive impairment scores." (PMID 39337560, 2024).
colitis (1 paper, 2025). Inflammation of the colon. "In contrast, our study showed that Rab12 deletion significantly reduced phosphorylated RAB10 levels in colon tissue and led to a marked improvement in colitis severity across multiple readouts." (PMID 41031878, 2025). "Rab12 KO reduces RAB10 phosphorylation and alleviates colitis severity in Lrrk2N2081D mice." (PMID 41031878, 2025). "Analysis of a subset of N2081D male mice with severe colitis symptoms showed a striking increase in phosphorylated RAB10 in DSS-treated colon tissue, compared with untreated animals, indicating the N2081D mutation’s effects may be further amplified by severe inflammation." (PMID 41031878, 2025). "A surprising finding in our study is that dietary administration of the LRRK2 kinase inhibitor MLi-2 did not significantly alleviate DSS-induced colitis in N2081D mice despite reducing RAB10 phosphorylation in colon tissue." (PMID 41031878, 2025).
colorectal tumors (1 paper, 2023). "Supporting this view, RAB10 expression is increased in colorectal tumors that have deep deletions of SMAD4 as compared with tumors with gain of SMAD4." (PMID 37377893, 2023). "At the clinical level, TCGA analysis shows that RAB10 is significantly less expressed in colorectal tumors with a gain of SMAD4 as compared with tumors with deep deletion of SMAD4 (*, P = 0.0391 gain vs. deep deletion), suggesting that RAB10 expression is upregulated in absence of SMAD4." (PMID 37377893, 2023).
endotoxemia (1 paper, 2022). "We found that Rab10 active-site mutant altered the expression of cell surface EGFR in RAW264.7 macrophages during endotoxemia but did not affect total protein levels of EGFR expression." (PMID 36344490, 2022).
Fanconi anemia (1 paper, 2023). Fanconi anemia (FA) is a hereditary DNA repair disorder characterized by progressive pancytopenia with bone marrow failure, variable congenital malformations and predisposition to develop hematological or solid tumors. "GSEA KEGG analysis suggested that RAB10 may be involved in BC progression through the Hedgehog signaling pathway, Fanconi anemia pathway, Hippo signaling pathway, and other pathways." (PMID 37709911, 2023). "Furthermore, GSEA KEGG analysis demonstrated that RAB10 interacts with the Hedgehog signaling pathway, Fanconi anemia pathway, Hippo signaling pathway (multiple species), and PPAR signaling pathway." (PMID 37709911, 2023).
gastric adenocarcinoma (1 paper, 2022). "Interestingly, a novel form of ALK gene fusion was identified, being the first gastric adenocarcinoma case with RAB10-ALK fusion." (PMID 36145589, 2022).
HCMV infection (1 paper, 2021). "Similar to that observation in HCMV infection, Pitstop 2 did not significantly affect MCMV infected cells, neither on the pericentriolar Rab10 accumulation in the preAC at 16 hpi nor in the AC at 40 hpi." (PMID 34575026, 2021).
malaria (1 paper, 2012). Malaria is a serious and sometimes fatal disease caused by a parasite that commonly infects a certain type of mosquito which feeds on humans. "Therefore, the only two Rab GTPases that had their expression increased after incubation with both bacteria and the malaria parasite were Rab10 and Rab20." (PMID 22911692, 2012). "The results showed that, compared to the negative control, the live malaria parasite was able to induce an increase in the expression of Rab1a, Rab1b, Rab7a, Rab10, Rab14, Rab20, Rab27a, Rab32 and Rab38." (PMID 22911692, 2012).
neuritis (1 paper, 2025). A neuropathy arising from inflammation of one or more nerves. "[Ca2+]ER in neuritis was also reduced by 15% in Rab10 KD neurons." (PMID 40172954, 2025).
pancreatic cancers (1 paper, 2023). "Comparable biological tendency was observed in pancreatic tumors, in which a decrease of RAB10 expression level seemed to be associated with a gain of SMAD4." (PMID 37377893, 2023). "The small GTPase protein RAB10 was identified and validated as a susceptibility gene in SMAD4-altered colorectal and pancreatic cancer cells." (PMID 37377893, 2023). "Our data show that RAB10 KO decreases proliferation preferentially of SMAD4-deficient colorectal and pancreatic cancer cell lines." (PMID 37377893, 2023). "All together, these data showed that RAB10 depletion contributed to decrease the cell fitness of SMAD4-deficient cells and that RAB10 might be a susceptibility gene in SMAD4-altered colorectal and pancreatic cancer cells." (PMID 37377893, 2023). "In summary, our work identifies RAB10 as a potentially synthetic lethal gene in SMAD4-negative colorectal and pancreatic cancer cells." (PMID 37377893, 2023).
prostate carcinoma (1 paper, 2019). A carcinoma that arises from epithelial cells of the prostate gland. "From this list, PABPC1, CLIC1, RAB10, and PKM2 have been identified as a potential marker for (prostate) cancer." (PMID 31018022, 2019).
virus infection (1 paper, 2025). "This study focused on Rab10 and its role in the autophagy pathway within shrimp, as it pertains to defending against viral infections." (PMID 40001579, 2025).